IL17RA (interleukin 17 receptor A)
Diseases named in the same sentence as IL17RA in open-access papers (continued):
Sharing a sentence is not in itself a finding about the gene and the disease.
tongue cancer (1 paper, 2019). A malignant neoplasm affecting the tongue. "Interestingly, the mRNA of the IL-17F receptors (IL-17RA and IL-17RC) were decreased in both HSC-3 and SCC-25 tongue cancer cell lines compared to normal HOKs." (PMID 31083515, 2019).
tuberculosis (1 paper, 2016). A chronic, recurrent infection caused by the bacterium Mycobacterium tuberculosis. "The IL-17RA pathway was recently shown to be critical in CXCL1 and CXCL5-mediated early neutrophil recruitment after M. tuberculosis H37Rv infection." (PMID 27853279, 2016).
type-2 diabetes (1 paper, 2023). "Despite the absence of monoclonal antibodies against known type-2 diabetes small molecule targets ABCC8, ABCC9, DPP4, and KCNJ11, these genes demonstrated AB tractability estimates greater than 60%, along with interleukin receptors IL4R and IL17RA." (PMID 37225853, 2023).
ulcers (1 paper, 2021). "We then determined if neutrophils/polymorphonucler cells (PMNs) were localizing to ulcers in the absence of IL-17RA." (PMID 34220843, 2021).
upper respiratory tract infection (1 paper, 2023). "Thus, our data reveal the pathologic contribution of IL-17RA during IAV upper respiratory tract infection." (PMID 38060620, 2023).
viral myocarditis (1 paper, 2013). Myocarditis that is caused by an infection with a viral agent. "Therefore, this study investigated the role of the adenovirus-containing IL-17 receptor A (Ad-IL17RA:Fc) in the progression of acute viral myocarditis to DCM, with emphasis on the occurrence of chronic fibrosis post-viral infection." (PMID 23977238, 2013).
vitiligo (1 paper, 2011). Generalized well circumscribed patches of leukoderma that are generally distributed over symmetric body locations and is due to autoimmune destruction of melanocytes. "Double immunofluorescencestaining of IL-17A and IL-17RA was performed to identify receptor bound IL-17A.We observed that 50–60% of IL-17RA positive cells are also IL-17Apositive in leading edge vitiligo biopsies." (PMID 21541348, 2011).
tumor (93 papers, 2010 to 2026). "In pancreatic ductal adenocarcinoma, IL-17A promotes tumor progression by inducing the differentiation of cancer-associated fibroblasts via IL-17RA and TNF signaling, creating a tumor-promoting stromal environment." (PMID 40536951, 2026). "Contrary to expectations, global IL‐17RA deficiency (Il17ra−/−) markedly accelerated tumor progression in both subcutaneous and orthotopic PDAC models." (PMID 38585232, 2024). "A recent study revealed that C. albicans promoted OSCC development via the IL-17A/IL-17RA-macrophage axis, and the tumor-associated macrophages (TAMs) attracted by C. albicans infection polarized into the M2 phenotype with high expression of PD-L1." (PMID 38515216, 2024). "High IL‐17RA expression was significantly associated with clinical stage, tumor invasion (T), lymph node metastasis (N), distal metastasis (M), differentiation, CEA, poor OS, and CRC‐specific survival." (PMID 38491831, 2024). "In this study, we revealed that low IL‐17RA expression is associated with good prognosis and tumor progression." (PMID 38491831, 2024). "A novel pro-tumorigenic Tc17 cell has been identified in pancreatic ductal adenocarcinoma, which accelerates tumor growth through IL-17RA-dependent modification of cancer-associated fibroblast." (PMID 39906741, 2024). "Tumor-associated macrophage accumulation was associated with IL-17A/IL-17RA signaling pathway during C. albicans infection." (PMID 37067414, 2023). "Genes encoding cognate receptors Il17ra and Il17rc were relatively increased, respectively, in immune cells (particularly neutrophils and macrophages) and Basal tumor cells." (PMID 34408137, 2021). "Interleukin 17 receptor A (IL17RA) polymorphisms, which play an important role in tumor development, have been found to influence both the unilateral and bilateral development of PTC." (PMID 31842912, 2019). "Neo-antigen load also correlated with increased expression of IL23A, IL21, and IL17RA, all of which are players in the Th17 T cell pathway, which is implicated in both tumorigenesis as well as the anti-tumor immune response." (PMID 29487705, 2018). "In addition, dual oxidase 2 (DUOX2), a gene whose expression is differentially modulated by IL‐17A, was primarily detected in tumor cell clusters derived from mice with IL‐17RA deficiency." (PMID 38585232, 2024). "In addition, it has been shown that C. albicans promotes development of 4NQO-induced oral cancer via the IL-17A/IL-17RA induced tumor associated macrophages." (PMID 37373022, 2023). "The IL-17/IL-17RA pathway mediates this cascade via a downstream positive circuit, directly stimulating tumor formation." (PMID 41438576, 2026). "In this retrospective study, patients with CRC with high IL-17RA expression in their tumor tissue had a poorer prognosis than those with low IL-17RA expression." (PMID 41438576, 2026). "For example, IL-17RA has been shown to mediate pro-inflammatory signaling pathways that contribute to tumor growth and resistance to therapy." (PMID 41438576, 2026). "Non-canonical CD8+ T-cell subpopulation producing IL-17A (Tc17) accelerates tumor growth via IL-17RA-dependent stroma modification, as IL-17A and TNF synergistically induce differentiation of inflammatory CAFs (iCAFs) by IL-17RA." (PMID 40427098, 2025). "In tumor‐bearing mice, mice bearing control cells had significantly larger tumor volumes than mice bearing IL‐17RA knockdown cells." (PMID 38491831, 2024). "The univariate and multivariate analysis results, including Il‐17RA, age, tumor stage, CEA, CA19‐9 and TILs, were used to predict CRC‐specific survival." (PMID 38491831, 2024). "Il17rafl/fl; Villin‐Cre mice, with specific enteric deletion of IL‐17RA, exhibited the most aggressive tumor growth, accompanied by notable neurological signs and symptoms." (PMID 38585232, 2024). "Theoretically, IL‐17RA engagement enhances tumor proliferation, inflammatory responses, and lymphocyte infiltration, resulting in poor clinical prognosis." (PMID 38491831, 2024).
tumor (continued). "Ablation of IL-17RA, specifically in Tregs, resulted in increased Th17 cells, and exacerbated tumor development." (PMID 38947320, 2024). "Studies have revealed that among these cytokines, the IL-17 family (IL-17A to IL-17 F) and their receptor (IL-17RA to IL-17RE) are involved in Th17 responses, and they can participate in pro-tumor or anti-tumor responses depending on their phenotype." (PMID 38515019, 2024). "Knockdown of IL‐17RA inhibited tumor growth and vascularity and decreased the population of Tregs and MDSCs in mouse tumors." (PMID 38491831, 2024). "Il17rafl/fl; Villin‐Cre mice, featuring targeted enteric deletion of IL‐17RA, exhibited the most pronounced tumor growth, coupled with discernible neurological manifestations and symptoms." (PMID 38585232, 2024). "In investigating the correlation between microbial dysbiosis and tumor growth, the researchers synergistically combined ampicillin with anti‐IL‐17RA antibodies, resulting in an observed enhanced antitumor effect." (PMID 38585232, 2024). "Tumor cells can release the chemokine (C-C motif) ligand 2 (CCL2) upon activating IL-17RA signaling to attract macrophages into the tumor microenvironment." (PMID 39272855, 2024). "Since we found that high levels of IL‐17RA is negatively associated with CRC patient survival, besides, the population of Treg and MDSC cells was significantly lower in IL‐17RA‐knockdown tumor of mouse model." (PMID 38491831, 2024). "Meanwhile, as IL-17RA and IL-17RC are also expressed in TAMs, IL-17 in tumor tissue can boost the recruitment and migration of TAMs." (PMID 39906741, 2024). "A tumor‐bearing mice model was executed to evaluate the role of IL‐17RA in tumor growth, vascularity and population of infiltrating immune cells." (PMID 38491831, 2024). "In a tumor‐bearing mouse model, decreased IL‐17RA expression significantly repressed tumor growth and vascularity and reduced the population of regulatory T cells (Tregs) and myeloid‐derived suppressor cells (MDSCs)." (PMID 38491831, 2024). "Collectively, our finding revealed that C. albicans promoted OC development via the IL-17A/IL-17RA-macrophage axis, opening perspectives for revealing C. albicans-tumor immune microenvironment links." (PMID 37067414, 2023). "It is obvious that the three receptors IL-17RA/RB/RD play a key role in affecting the signaling pathway of tumor progression and tumor development." (PMID 37686343, 2023). "In our study, compared with the normal liver tissues, we found the increased expression of IL-17RA in tumor adjacent tissues." (PMID 36172147, 2022). "The treatment with centrinone slightly exacerbated tumor burden in WT male mice, but the condition was improved by Il17ra(T779A)-KI and Il17rc-KO." (PMID 36009523, 2022). "MeRIP-seq revealed the reduction of m6A mRNA methylation of IL-17RA in tumor adjacent tissues with chronic inflammation, suggesting the potential role of IL-17RA in the inflammation-carcinogenesis transformation of HCC." (PMID 36172147, 2022). "FTO elevated in tumor adjacent tissues of the liver and contributed to the m6A mRNA demethylation of IL-17RA, which led to the elevated translational regulation of IL-17RA, exacerbating liver inflammation and worsening liver function." (PMID 36172147, 2022). "Even though the proliferation of the epidermis in both male and female mice was significantly induced by DMBA/TPA among WT, Il17ra(T779A)-KI, and Il17rc-KO mouse strains, Il17ra(T779A)-KI alleviated tumor formation and Il17rc-KO totally abolished it." (PMID 36009523, 2022). "IL17A exerts its tumor-promoting activity through its type A receptor (IL-17RA), which is expressed in various cell types in the tumor microenvironment, including hematopoietic cells, fibroblasts, and epithelial cells." (PMID 34367971, 2021). "Several clinical studies showed that IL-17RA expression was higher in various tumor tissues, including NSCLC." (PMID 33802737, 2021).
tumor (continued). "Genetic evidence shows that IL-17 can directly promote proliferation of transformed colonic epithelial cells tumor through its type A receptor (IL-17RA)." (PMID 33889575, 2021). "Ablation of IL-17RA in the mouse sporadic tumor model resulted in elevated expression of CTLA-4, a cell surface protein that is constitutively expressed in Tregs and mediates part of their immune suppressive function." (PMID 31775909, 2019). "Previous reports have suggested that IL-17 signals through interactions with transmembrane receptors composed of IL-17RA and IL-17RC heterodimers induce a broad tissue response at the site of inflammation and increase pro-tumor activity on tumor cells." (PMID 29515773, 2018). "This initiation and promotion effects by Th17 cells are mediated through their interaction with tumor-initiating cells and PanIN cells, both expressing IL-17 receptor A (IL-17RA)." (PMID 29379802, 2017). "The mRNA expression of IL-17RA was increased in 56 of 72 (77.8%) tumor samples compared with its matched counterparts (P < 0.01)." (PMID 28035060, 2017). "IL-17E, through binding to its own receptor IL-17RB or IL-17RA, shows different properties from IL-17A and IL-17 F in tumor fields." (PMID 27716046, 2016). "We also observed that IL-17RA levels were mainly increased in the epithelial tumor cells, though IL-17RA levels in the stromal cells were also increased in obese mice compared to lean mice (IHC data not shown)." (PMID 26871944, 2016). "More importantly, IL-17 directly repressed expression and function of miR-192; and miR-192 sequentially targeted IL-17RA and IL-17RE, which binds the ligand IL-17 to function in tumor microenvironment." (PMID 25489847, 2014). "Furthermore, knockdown of IL‐17RA suppresses tumor vascularity and growth, and reduces the population of Tregs and MDSCs in mouse tumors." (PMID 38491831, 2024). "Furthermore, decreased IL‐17RA expression inhibited tumor growth and modulated tumor‐infiltrating immune cells in mice." (PMID 38491831, 2024). "However, our previous studies indicated that IL-17RA is highly expressed in mouse tumor tissues, promoting CRC occurrence and development." (PMID 39906741, 2024). "Thus, IF was performed and showed that more macrophages surrounded the epithelial cells and tumor cells with higher IL-17RA expression." (PMID 37067414, 2023). "Thus, the OC cells with IL-17RA activation released more CCL2 to attract macrophages into the tumor environment." (PMID 37067414, 2023). "Tumor incidence in WT mice was also significantly higher than in the Il17ra(T779A)-KI mice." (PMID 36009523, 2022). "Importantly, the upregulation of IL-17RA in the tumor adjacent tissues was confirmed at protein level determined by Western blot." (PMID 36172147, 2022). "The decreased m6A mRNA modification of IL-17RA in tumor adjacent tissues of the liver may require a larger cohort to validate." (PMID 36172147, 2022). "Tumor tissue from Il17ra−/− mice presented lower IL6 mRNA expression than that from Il17ra+/− mice." (PMID 33578830, 2021). "Notably, simultaneous silencing of β-catenin and IL-17RA more strongly inhibited tumorigenicity and tumor growth compared to single-gene silencing in miR-125a-overexpressing stromal cell xenografts." (PMID 30388623, 2018). "IL-23A may induce the secretion of IL-17A activate IL-17A/IL-17RA/NF-κB signaling in tumor microenvironment." (PMID 25349535, 2014). "Given that many types of tumor cells bear IL-17 receptor alpha (IL-17RA), the specific receptor for IL-17, IL-17 may have a direct impact on the biological behavior of tumor cells in the local microenvironment." (PMID 22171994, 2011). "First, we determined whether IL‐17RA plays a role in tumor migration and invasion." (PMID 38491831, 2024). "Finally, to confirm that IL-17 signaling in tumor rather than host cells is required for tumor progression, we established mice globally deficient in IL-17RA." (PMID 38062130, 2023).
tumor (continued). "Specific inhibitors of IL-17RA signaling, such as the STAT3 inhibitor Stattic, reduced the expression of CD133, LGR5, ALDHA1, SOX2 and c-MYC, as well as tumor sphere formation in SW620 cells." (PMID 41438576, 2026). "Implication of IL-17RA in the renewal of glioma cells suggested its potential role in promoting CSC and tumor advancement." (PMID 41438576, 2026). "Our recent study demonstrated that reduced IL-17RA expression correlates with favorable prognosis in CRC patients and suppresses tumor growth in murine models." (PMID 41438576, 2026). "This study showed that the gene expression of IL-17RA, IL-17RC, and CXCR2 in tumor tissues was significantly higher than in normal tissues isolated from patients with BC." (PMID 38515019, 2024). "Based on multivariate analysis, IL‐17RA is a predictor of poor CRC‐specific survival based on multiple logistic regression analysis after adjusting for age, tumor stage, CEA, CA19‐9, and TILs." (PMID 38491831, 2024). "Studies have revealed that the IL-17A/IL-17RA signaling pathway is activated in oral cancer cells infected with Candida albicans, which induces CCL2 and attracts macrophages into the tumor environment." (PMID 39906741, 2024). "Further analyses of clinical datasets revealed correlations of IL-17 receptor A (IL-17RA) and IL-17RC expressions with a poor prognosis of LUAD patients with a smoking history or with higher levels of tumor-infiltrating lymphocytes." (PMID 33802737, 2021). "Despite the expression of IL-17RA and IL-17RC on 4T1 TNBC tumor cells, 4T1 cells transduced with AdIL-17A and Addl showed similar growth kinetics in vitro, suggesting that IL-17A stimulation has a little direct effect on the growth of 4T1 TNBC cells." (PMID 32770025, 2020). "This IL-17-tumor cell signaling is necessary for the survival and outgrowth of early CRC lesions, and ablation of IL-17RA, the common receptor of IL-17 family cytokines, resulted in marked reduction in tumor numbers in mouse colon." (PMID 31775909, 2019). "For instance, inhibiting IL-17A at tumor sites significantly suppresses CD31, MMP9, and VEGF expression in the tumor, while activating its receptor (IL-17RA) promotes early tumor development." (PMID 29983876, 2018). "The anti-tumor mechanisms depend on inhibition of EGFR- and IL-17RA-signaling and enhancement of anti-tumor immune responses." (PMID 29212184, 2017). "Fibroblasts express IL-17RA in PDAC and promote Tc17-driven tumor growth." (PMID 39906741, 2024). "IL-17A/IL-17RA induced CCL2 and attracts macrophages into the tumor environment." (PMID 39906741, 2024). "Multivariate analysis revealed that IL‐17RA was a predictor of CRC‐specific survival (HR = 2.221; CI = 1.135–4.345; p = 0.02) based on multiple logistic regression analysis after adjusting for age, sex, tumor stage, TILs, and CEA and CA19‐9 levels." (PMID 38491831, 2024). "Interestingly, we found their receptors, IL17RA/IL17RC for IL17A/IL17F, IL10RB/IL22RA1 for IL22, and IL20RA/IL10RB for IL26, were upregulated in tumor cell than in normal epithelial cells." (PMID 35999201, 2022). "Il17ra(T779A)-KI did not alter tumor multiplicity, but Il17rc-KO significantly alleviated the growth of tumors." (PMID 36009523, 2022). "However, m6A mRNA modification of IL-17RA between tumor adjacent tissues and HCC tumor tissues showed little difference, indicating that the m6A mRNA demethylation of IL-17RA has become a critical event in the early stage of HCC prior to tumor formation." (PMID 36172147, 2022). "In male mice, tumor volume was not significantly reduced in Il17ra(T779A)-KI mice compared with WT mice, but centrinone treatment enhanced this reduction." (PMID 36009523, 2022). "Given that the expression of IL-17RA was considerable in HCC cells, we thus hypothesize that IL-17-mediated tumor-promoting role involved a direct effect on HCC cells." (PMID 22171994, 2011).
tumor (continued). "IL-17RA overexpression significantly increased CSC marker expression, including cluster of differentiation 133 (CD133), leucine-rich repeat-containing G protein-coupled receptor 5 (LGR5), sex determining region Y-box 2 (SOX2), and enhanced tumor sphere formation and 5-FU resistance in SW620 cells." (PMID 41438576, 2026). "Additionally, some IRGs with copy number amplification (HMGB1, IL17RA, and BAX) showed increased expression in tumor tissues, while some IRGs with copy number deletions (IL10, NT5E, and ENTPD1) showed decreased expression in tumor tissues." (PMID 36386817, 2022). "Since the high levels of IL-17 production in PBMCs were consistent with HNC progression and the expression of IL-17RA (the predominant IL-17 receptor) is also increased, we presumed that IL-17 may have a direct effect on tumor cells in HNC to mediate tumor promotion." (PMID 29515773, 2018). "IL-17/IL-17RA subsequently activated NF-κB pathway and STAT3 pathway, triggering the transcription of various downstream target genes, including PD-L1, Cyclin family members, MMPs, and EMT makers, which may lead to immune evasion, tumor growth, and tumor invasion of PCa." (PMID 40055805, 2025). "Cyclin E proteolysis might be a tumor specific mechanism as IL-17A failed to up-regulate the generation of LMW-E forms in the non-transformed mammary epithelial MCF10A cells although these cells express significant levels of IL-17RA and IL-17RC." (PMID 26154409, 2015).